QTMAN (queuosine-tRNA mannosyltransferase)
Description:
Glycosyltransferase that specifically catalyzes mannosylation of cytoplasmic tRNA(Asp) modified with queuosine at position 34 (queuosine(34)). Mannosylates the cyclopentene moiety of queuosine(34) in tRNA(Asp) to form mannosyl-queuosine(34). Mannosylation of queuosine(34) in tRNA(Asp) is required to slow-down elongation at cognate codons, GAC and GAU, thereby regulating protein translation.
Synonyms: GTDC1; FLJ11753; Hmat-Xa; mat-Xa
Tractability: PROTAC: its protein half-life has been measured.
Gene: Protein-coding gene on chromosome 2 (143,938,068 to 144,333,107, reverse strand). Ensembl gene ENSG00000121964.
Subcellular location: Cytoplasm; Nucleus
Subcellular location (Human Protein Atlas): Cytosol
Gene Ontology:
Molecular function: tRNA-queuosine(34) beta-mannosyltransferase activity; glycosyltransferase activity
Biological process: regulation of translation; tRNA modification; tRNA wobble guanine modification
Cellular component: cytoplasm; nucleus
Genetic constraint (gnomAD): Loss-of-function variants: 20 observed, 19.46 expected, observed/expected ratio (o/e) 1.03, 90% interval 0.72 to 1.49. The upper end of that interval is the gene's LOEUF score, 1.49, which puts it in group 6 of 6, group 1 being the genes least tolerant of losing a copy. Missense variants: 230 observed, 255.99 expected, observed/expected ratio (o/e) 0.9, 90% interval 0.81 to 1. Synonymous variants: 100 observed, 101.31 expected, observed/expected ratio (o/e) 0.99, 90% interval 0.84 to 1.17.
Homologues: Orthologues: chimpanzee GTDC1 (99% identical), macaque GTDC1 (95% identical), dog GTDC1 (88% identical), rabbit GTDC1 (87% identical), guinea pig GTDC1 (86% identical), rat Gtdc1 (79% identical), mouse Gtdc1 (79% identical), tropical clawed frog gtdc1 (64% identical), pig GTDC1 (62% identical), zebrafish gtdc1 (58% identical), Drosophila melanogaster CG15914 (39% identical).
Diseases named in the same sentence as QTMAN in open-access papers:
QTMAN is named in the same sentence as 11 diseases in open-access papers, as found by Europe PMC text mining. Sharing a sentence is not in itself a finding about the gene and the disease.
QTMAN shares sentences with these, for which no sentence is quoted: neurodevelopmental disorder (2 papers); chondrodysplasia (1); developmental delay (1); epilepsy (1); epileptic syndrome (1); infection (1); Intellectual disability (1); microcephaly (1); Oral ulcer (1); osteoarthritis (1); Rett syndrome (1).